ANKRD55 (ankyrin repeat domain 55)
Synonyms: FLJ11795
Tractability: No criterion of Open Targets' tractability assessment is met for any kind of drug.
Gene: Protein-coding gene on chromosome 5 (56,099,680 to 56,233,330, reverse strand). Ensembl gene ENSG00000164512.
Subcellular location (Human Protein Atlas): Nuclear speckles; Nucleoplasm; Cytosol
Gene Ontology:
Molecular function: protein binding
Genetic constraint (gnomAD): Loss-of-function variants: 38 observed, 59.08 expected, observed/expected ratio (o/e) 0.64, 90% interval 0.5 to 0.84. The upper end of that interval is the gene's LOEUF score, 0.84, which puts it in group 3 of 6, group 1 being the genes least tolerant of losing a copy. Missense variants: 725 observed, 791.4 expected, observed/expected ratio (o/e) 0.92, 90% interval 0.86 to 0.97. Synonymous variants: 261 observed, 302.7 expected, observed/expected ratio (o/e) 0.86, 90% interval 0.78 to 0.95.
Homologues: Orthologues: chimpanzee ANKRD55 (99% identical), macaque ANKRD55 (97% identical), pig ANKRD55 (90% identical), dog ANKRD55 (89% identical), guinea pig ANKRD55 (88% identical), rat Ankrd55 (86% identical), mouse Ankrd55 (86% identical), rabbit ANKRD55 (79% identical), tropical clawed frog ankrd55 (65% identical), zebrafish ankrd55 (57% identical). Paralogues in human: ANKRD28 (27% identical), ANKRD52 (27% identical), ANKRD44 (26% identical).
Diseases named in the same sentence as ANKRD55 in open-access papers:
ANKRD55 is named in the same sentence as 38 diseases in open-access papers, as found by Europe PMC text mining. Sharing a sentence is not in itself a finding about the gene and the disease. The quoted sentences say what the papers report.
autoimmune disease (7 papers, 2017 to 2023). A disorder resulting from loss of function or tissue destruction of an organ or multiple organs, arising from humoral or cellular immune responses of the individual to their own tissue constituents. "Other SNPs in ANKRD55, located like rs7731626 in intronic areas next to exon 6, have, as well, been associated with the risk for autoimmune disease with genome-wide significance levels." (PMID 35111166, 2021). "Risk for autoimmune disease conferred by rs7731626 is correlated with increased mRNA expression of ANKRD55 and IL6ST and with reduced cis CpG methylation in CD4+ T cells." (PMID 35111166, 2021). "The risk alleles of associated eQTL SNPs such as rs6859219, rs71624119 and rs10065637 are shared among autoimmune diseases and are associated with higher expression of ANKRD55 in CD4+ T lymphocytes." (PMID 31620119, 2019). "The ankyrin repeat domain-55 (ANKRD55) gene contains intronic single nucleotide polymorphisms (SNPs) associated with risk to contract multiple sclerosis, rheumatoid arthritis or other autoimmune disorders." (PMID 31620119, 2019). "The ANKRD55 gene contains many SNPs that are associated with different autoimmune disease risks." (PMID 35983018, 2022). "While the exact function of ANKRD55 is unclear, there may be a link between genetic variants of ANKRD55 and autoimmune diseases." (PMID 35983018, 2022). "However, GWAS data suggest that ANKRD55 is a genetic predisposition factor for such autoimmune diseases as Crohn's disease, multiple sclerosis (MS), and rheumatoid arthritis (RA)." (PMID 35983018, 2022). "For the typical autoimmune diseases, we designed a case-control study to study the relationship between the AITDs and ANKRD55, which may reveal some underlying mechanisms of AITDs." (PMID 35983018, 2022). "Thus, ANKRD55 appears as the nearest annotated gene affected by the risk eQTL SNP rs6859219 or its proxies that emerged from GWAS on various autoimmune diseases." (PMID 31620119, 2019). "Although the precise function of ANKRD55 is still unknown, a link between genetic variants of ANKRD55 and autoimmune diseases may exist." (PMID 28470010, 2017). "ANKRD55 encodes ankyrin repeat domain-containing protein 55, which mediates protein–protein interactions and may have a role in autoimmune diseases, whereas MAP3K1, which is also known as MEK kinase 1, is a serine/threonine kinase that belongs to the mitogen-activated protein kinases (MAP3K) family." (PMID 36980976, 2023). "Single nucleotide polymorphisms (SNPs) in TNFSF4 and ANKRD55 genes have been shown to be associated with several autoimmune diseases, although whether these genes are susceptibility genes for dermatomyositis/polymyositis (DM/PM) has, to date, not been reported." (PMID 28470010, 2017). "Many of these genes have either known roles in Treg differentiation, stability and function (CD48, IL6ST, EZR, ELMO1, IL18R1), or altered expression in human Treg in autoimmune disease (SLAMF1, ANKRD55, TAGAP)." (PMID 35773720, 2022). "As ANKRD55’s proximate neighbor, IL6ST is especially striking due to its well-documented role in inflammation and autoimmune disease." (PMID 35111166, 2021). "Based on human transcriptomic data, ANKRD55 is expressed in the ovaries, testes, endometrium, CD4+T cells, and monocytes, the latter two of which may be more important in autoimmune diseases." (PMID 35983018, 2022).
multiple sclerosis (7 papers, 2019 to 2023). A progressive autoimmune disorder affecting the central nervous system resulting in demyelination. "Intronic single-nucleotide polymorphisms (SNPs) in the ANKRD55 gene are associated with the risk for multiple sclerosis (MS) and rheumatoid arthritis by genome-wide association studies (GWAS)." (PMID 35111166, 2021). "Although the biologic function of ANKRD55 gene products remains unclarified, single nucleotide polymorphisms in ANKRD55 are risk factors for multiple immune diseases, including multiple sclerosis, Crohn’s Disease, diabetes, and inflammatory myopathies." (PMID 34830268, 2021). "A previous study identified rs7731626 as likely causal for multiple sclerosis and RA and was also a T cell-specific eQTL for both IL6ST and ANKRD55." (PMID 37289818, 2023). "However, some studies reported ANKRD55 expression in cerebral and spinal neurons suggesting its possible role in pathogenesis of multiple sclerosis." (PMID 33536079, 2021).
rheumatoid arthritis (7 papers, 2019 to 2024). A chronic, systemic autoimmune disorder characterized by inflammation in the synovial membranes and articular surfaces. "In rheumatoid arthritis, an intronic variant of ANKRD55 was associated with the disease, and there was a significant correlation between CRP levels and the variant." (PMID 37238156, 2023). "In addition, MTWAS identified that the expression of ANKRD55 in colon transverse is significantly associated with rheumatoid arthritis (P = 4.69 × 10−8)." (PMID 38982044, 2024).
type 2 diabetes (3 papers, 2015 to 2022). "Previous studies have reported that single nucleotide polymorphisms in ANKRD55, an autoimmune risk protein, are associated with type 2 diabetes susceptibility." (PMID 33827590, 2021).
autoimmune disorders (2 papers, 2019 to 2021). "Though little is known about ANKRD55’s biological relevance to autoimmunity, its expression in immature moDC and upregulation by retinoic acid and downregulation by TLR maturation factors suggest a specific role associated with the differentiation stage of monocyte precursor to DCs." (PMID 35111166, 2021).
diabetes (2 papers, 2021 to 2022). "Interestingly, Ankrd55 has also already been shown to be implicated in diabetes development as the human ANKRD55 locus is associated with both body composition and diabetes." (PMID 35328627, 2022).
Insulin resistance (2 papers, 2018 to 2021). Increased resistance towards insulin, that is, diminished effectiveness of insulin in reducing blood glucose levels. "Notably, one region on BTA20, which harbors the gene ANKRD55, implicated in adipocyte differentiation and insulin resistance, showed significant effects on both visceral fat accumulation and displaced abomasum." (PMID 35058972, 2021). "The whole-body insulin resistance possibly promoted by ANKRD55 would endorse the insulin resistance stimulated by cytokines release from visceral fat and the impaired glucose-stimulated insulin secretion in pancreatic β cells mediated by the significant gene TSHZ1." (PMID 35058972, 2021).
Arthritis (1 paper, 2020). Inflammation of a joint. "We validated cis-meQTL effects at 3 loci implicated by CIT (cg21124310/ANKRD55, cg07522171/JAZF1, and cg17134153/FCRL3) in an independent cohort of 39 patients with early arthritis using pyrosequencing." (PMID 31945409, 2020).
asthma (1 paper, 2020). "For example, strong evidence is found for site-specific DNAm as an intermediary via which disease variants regulate ORMDL3, GSDMB, and JAZF1 expression by CD4+ T cells in RA, MS, and asthma, and a similar mechanism in relation to ANKRD55 and IL6ST is limited to RA and MS." (PMID 31945409, 2020).
autoimmune thyroid disease (1 paper, 2022). Inflammatory disease of the thyroid gland due to autoimmune responses leading to lymphocytic infiltration of the gland. "Recent studies have shown that Ankyrin Repeat Domain 55 (ANKRD55) gene polymorphism is a risk factor for multiple autoimmune diseases, but its association with autoimmune thyroid diseases (AITDs) has not been reported." (PMID 35983018, 2022).
brain tumors (1 paper, 2021). "However, the combination of strong immunopositivity for both, SOX10 and ANKRD55 proved highly specific for CNS_NBL, both in institutionally diagnosed CNS-PNET cohort and extended set of malignant pediatric brain tumors." (PMID 33536079, 2021). "Therefore, in contrast to SOX10, ANKRD55 has not been systematically tested for its expression in human brain tumors." (PMID 33536079, 2021).
ciliopathies (1 paper, 2017). "We also knocked down one of these proteins, ANKRD55, and showed a disruption in ciliogenesis, which strongly suggests a role in ciliopathies." (PMID 28596423, 2017). "Taken together, the interaction, localization, and genetic perturbation data all indicate that ANKRD55 interacts physically and functionally with the IFT‐B complex and strongly suggests that ANKRD55 is likely to play a role in human ciliopathies." (PMID 28596423, 2017).
glaucoma (1 paper, 2023). Increased pressure in the eyeball due to obstruction of the outflow of aqueous humor. "However, the possible relevance of ANKRD55 and MAP3K1 in glaucoma is unknown." (PMID 36980976, 2023).
inflammatory bowel disease (1 paper, 2025). A spectrum of small and large bowel inflammatory diseases of unknown etiology. "For 6 of these genes, a role in inflammatory bowel disease is supported by other criteria: GWAS associations with nearby SNPs (ANKRD55, LPP, PDLIM7), experimental perturbation (CCDC50, VCAM1), association with measured protein levels (IL6, VCAM1), or drug effects (IL6, VCAM1)." (PMID 40996888, 2025).
leprosy (1 paper, 2017). Leprosy is a chronic infectious disease affecting primarily the skin and peripheral nervous system. "Similarly, 7 of the 9 SNPs significantly heterogeneous between T1R and leprosy were eQTLs in either whole blood, rs3774937 (NFKB1), rs10065637 (ANKRD55), rs11150589 (ITGAL) and rs2836878 (lncRNA ENSG00000235888) or multiple tissues, rs4664304 (LY75), rs113653754 (HLA-DQB1) and rs4768236 (LRRK2)." (PMID 28222097, 2017).
pancreatic cancer (1 paper, 2021). "Among the four DNA transmethylases, only DNMT1 and DNMT2 were associated with ANKRD55 expression in pancreatic cancer." (PMID 33827590, 2021). "Additionally, MLH1 was positively associated with ANKRD55 expression, while EPCAM was negatively associated with ANKRD55 expression in pancreatic cancer." (PMID 33827590, 2021).
psoriasis (1 paper, 2025). An autoimmune condition characterized by red, well-delineated plaques with silvery scales that are usually on the extensor surfaces and scalp. "Finally, we conducted a replication analysis for SNPs in the TLR2, TLR5, and ANKRD55 genes, which were previously associated with treatment response to IL-23 inhibitors in a pre-selected SNP association study of a cohort of 18 patients with moderate-to-severe psoriasis from Spain." (PMID 41153410, 2025).
immune diseases (3 papers, 2021 to 2025). "For DGKQ, IL6ST and ANKRD55, decreased expression correlated with reduced immune disease risk, and increased expression with higher risk." (PMID 41361473, 2025).
cancer (2 papers, 2021). A tumor composed of atypical neoplastic, often pleomorphic cells that invade other tissues. "We further explored the relationships between ANKRD55 expression and immune checkpoints, DNA repair-related genes and DNA transmethylase in the pan-cancer profile." (PMID 33827590, 2021). "Results: 239 genes were identified for further survival analysis, 5 of which were overlapping genes across at least five cancer types, including RHEBL1, PDE4B, ANKRD55, EPHB2, and GIMAP7." (PMID 34262492, 2021). "The results showed that ANKRD55 expression was positively associated with most immune checkpoints in cancers, suggesting that although ANKRD55 predicted more intratumorally infiltrated CD8+ T cells, cancer cells may still evade immune system-mediated killing through immune checkpoint overexpression." (PMID 33827590, 2021).
tumor (2 papers, 2021). "Thus, all 20 CNS_NBL revealed intense ANKRD55 cytoplasmic expression in more than 75% of tumor cells." (PMID 33536079, 2021). "Therefore, we further studied whether ANKRD55 was differentially expressed between tumor and normal tissues." (PMID 33827590, 2021).
CNS neoplasms (1 paper, 2021). "Immunohistochemical detection of combined expression of SOX10 and ANKRD55 clearly identifies CNS_NBL discriminating them to other hemispheric CNS neoplasms harboring “PNET-like” microscopic appearance." (PMID 33536079, 2021). "Thus, an immunohistochemistry targeting SOX10 and ANKRD55 discriminates between CNS_NBL and other malignant pediatric CNS neoplasms (sensitivity—100% and specificity 98% for CNS_NBL)." (PMID 33536079, 2021). "All other malignant CNS neoplasms revealed no ANKRD55 staining besides a few ETMR samples which disclosed moderate staining in poorly differentiated areas (sensitivity—97% and specificity 95% for CNS_NBL)." (PMID 33536079, 2021).
ANKRD55 also shares sentences with these, for which no sentence is quoted: Crohn disease (4 papers); inflammatory myopathies (3); type 1 diabetes (2); Alzheimer disease (1); bipolar disorder (1); celiac disease (1); cognitive decline (1); common variable immunodeficiency (1); dermatomyositis (1); interstitial lung disease (1); juvenile idiopathic arthritis (1); lipodystrophy (1); open-angle glaucoma (1); polymyositis (1); post-traumatic stress disorder (1); schizophrenia (1); systemic lupus erythematosus (1).